ARHGAP12 (Rho GTPase activating protein 12)
Description:
GTPase activator for the Rho-type GTPases by converting them to an inactive GDP-bound state.
Synonyms: FLJ20737; FLJ10971; FLJ21785
Tractability: Antibody: its Gene Ontology location is reachable by antibodies, with medium confidence. PROTAC: ubiquitination databases record sites on it; its protein half-life has been measured.
Gene: Protein-coding gene on chromosome 10 (31,805,398 to 31,928,876, reverse strand). Ensembl gene ENSG00000165322.
Pathways (Reactome):
Signal Transduction: RAC1 GTPase cycle; RHOD GTPase cycle; RHOF GTPase cycle; RHOV GTPase cycle
Gene Ontology:
Molecular function: GTPase activator activity
Biological process: actin filament organization; morphogenesis of an epithelial sheet; negative regulation of small GTPase mediated signal transduction; phagocytosis, engulfment; small GTPase-mediated signal transduction; signal transduction
Cellular component: phagocytic cup; cytoplasm; plasma membrane
Genetic constraint (gnomAD): Loss-of-function variants: 44 observed, 83.11 expected, observed/expected ratio (o/e) 0.53, 90% interval 0.41 to 0.68. The upper end of that interval is the gene's LOEUF score, 0.68, which puts it in group 2 of 6, group 1 being the genes least tolerant of losing a copy. Missense variants: 840 observed, 923.92 expected, observed/expected ratio (o/e) 0.91, 90% interval 0.86 to 0.96. Synonymous variants: 285 observed, 318.23 expected, observed/expected ratio (o/e) 0.9, 90% interval 0.81 to 0.99.
Homologues: Orthologues: chimpanzee ARHGAP12 (99% identical), macaque ARHGAP12 (99% identical), pig ARHGAP12 (94% identical), guinea pig ARHGAP12 (93% identical), rabbit ARHGAP12 (92% identical), rat Arhgap12 (91% identical), mouse Arhgap12 (91% identical), dog ARHGAP12 (89% identical), tropical clawed frog arhgap12 (70% identical), zebrafish arhgap12b (62% identical), zebrafish arhgap12a (55% identical), Caenorhabditis elegans tag-325 (21% identical), and 1 more. Paralogues in human: ARHGAP27 (35% identical), ARHGAP9 (27% identical), ARHGAP15 (26% identical).
Diseases named in the same sentence as ARHGAP12 in open-access papers:
ARHGAP12 is named in the same sentence as 6 diseases in open-access papers, as found by Europe PMC text mining. Sharing a sentence is not in itself a finding about the gene and the disease. The quoted sentences say what the papers report.
bladder pain syndrome (1 paper, 2014). "Thus miR-199a-5p is expressed in the bladder's smooth muscle and urothelium and may play a role in bladder pain syndrome by suppressing LIN7C, ARHGAP12, PALS1, RND1 and PVRL1." (PMID 24574962, 2014).
Hypertension (1 paper, 2026). The presence of chronic increased pressure in the systemic arterial system. "However, we identified novel genes (SBF2, ARHGAP12, EPAS1, CLEC16A, and LRPPRC) to be associated with hypertension." (PMID 41898884, 2026).
pancreatic cancer (1 paper, 2024). "Three potential prognostic markers (ARHGAP5, ARHGAP11A, and ARHGAP12) for pancreatic cancer were identified." (PMID 38783033, 2024).
viral infection (1 paper, 2021). "Notably, we detect DIUs for several of the same genes (Setd5, Arhgap12, Gpbp1, and Eri2), suggesting that hnRNP K’s role in viral infection is conserved between mice and humans and may, in part, be mediated by the same alternative splicing events." (PMID 34305890, 2021).
tumor (4 papers, 2019 to 2024). "Gene ARHGAP12 encodes a junctional complex protein that affects tumour cell adhesion, scattering, and migration driven by hepatocyte growth factor." (PMID 31212796, 2019). "The expression level of ARHGAP12 was correlated with tumor size (p = 0.025)." (PMID 38783033, 2024). "Other RhoGAPs, such as ARHGAP4, ARHGAP6, ARHGAP9, ARHGAP12 and ARHGAP25, have also demonstrated tumor suppressor roles in different types of tumors 26-30." (PMID 36168627, 2022).
cancer (3 papers, 2019 to 2024). A tumor composed of atypical neoplastic, often pleomorphic cells that invade other tissues. "Downregulated ARHGAP12 has been related to the increased invasive growth of human cancer cell lines from lung epithelial cells, prostate, thyroid, and breast." (PMID 31212796, 2019). "By contrast, little is known about the role of ARHGAP12 in cancer." (PMID 38783033, 2024). "Aberrant expression of ARHGAP12, ATG5 and CNTN3 is associated with different types of carcinomas." (PMID 37026480, 2023).